CD4 (CD4 molecule)
Diseases named in the same sentence as CD4 in open-access papers (continued):
Sharing a sentence is not in itself a finding about the gene and the disease.
AIDS (continued). "The virus replicates in and kills CD4-expressing white blood cells, causing them to gradually decrease in number, ultimately leading to Acquired Immunodeficiency Syndrome (AIDS), where a patient is unable to fight off infections and disease." (PMID 24866200, 2014). "Acquired immunodeficiency syndrome (AIDS) is a disease of the human immune system caused by the HIV which destroys CD4+ T lymphocytes of the immune system that prevent infections." (PMID 24579041, 2014). "ART reduces the load of human immunodeficiency virus (HIV) and increases CD4 cell counts, delaying progression to acquired immune deficiency syndrome (AIDS) and reducing morbidity and mortality." (PMID 23304907, 2012). "The hallmark of HIV infection is progressive CD4+ T cell depletion leading to an increased risk for the development of opportunistic infections, acquired immune deficiency syndrome (AIDS), and death." (PMID 21490777, 2011). "If and when this evolution takes place, it is associated with a more rapid loss of CD4 T cells and accelerated progression to the acquired immunodeficiency syndrome (AIDS)." (PMID 21284905, 2011). "The CD4+ T cell count estimation became an important parameter for monitoring immune deficiency after the discovery of the acquired immune deficiency syndrome (AIDS)." (PMID 21245613, 2010). "Once in the human body, the virus replicates mainly in CD4+ lymphocytes and leads to a progressive degenerative immune deficiency disease, known as acquired immunodeficiency syndrome (AIDS)." (PMID 16939652, 2006). "CD4+ αβ T lymphocytes are likely to play a key role, as diseases caused by weakly virulent mycobacteria and the more virulent M.tb are common manifestations of acquired immunodeficiency syndrome (AIDS) and idiopathic CD4+ T lymphocytopenia." (PMID 40446017, 2025). "However, a major threat to this goal is late diagnosis, defined as diagnosis when the CD4 count is < 350 cells/μL or the patient presents with an acquired immune deficiency syndrome (AIDS)-defining event." (PMID 37470977, 2023). "However, it remains a significant problem in resource-limited settings and among patients with depressed CD4 and/or Acquired Immune Deficiency Syndrome (AIDS)-defining conditions." (PMID 36153612, 2022). "Persistently low CD4+ T cell counts can not only accelerate the progression of Acquired Immune Deficiency Syndrome (AIDS), but also accompany a high mortality rate from AIDS and non-AIDS-related illnesses, causing substantial difficulties in the management of infected individuals." (PMID 36325329, 2022). "Human immunodeficiency virus-1 (HIV-1) infection promotes an immune dysfunction characterized by an exacerbated systemic immune activation and chronic inflammation leading to the loss of CD4+ T-cells and the progression to acquired immunodeficiency syndrome (AIDS)." (PMID 35372109, 2022). "Assuming that cell-mediated immunity plays a key role in the early defense against M. ulcerans infection, and that the depletion of CD4 T cells in the acquired immunodeficiency syndrome (AIDS) caused by HIV weakens TH1 responses, BU-HIV coinfection has gained particular attention." (PMID 32100087, 2020). "Despite universal exposure, only 5%–10% of patients with HIV/acquired immune deficiency syndrome and profound CD4+ T-cell depletion develop disseminated cryptococcosis: host genetic factors may play a role." (PMID 33269293, 2020). "In most cases without any medical intervention, the anti-viral cellular responses fail to clear the virus, leading to a progressive loss of CD4+ T cells and eventually a state with a severely impaired immune system known as acquired immunodeficiency syndrome (AIDS)." (PMID 32775304, 2020). "Indeed, during HIV or SIV infection, with the loss of CD4+ T cells and disease progression to acquired immunodeficiency syndrome, Env-specific antibodies remain surprisingly high, indicating that at least some of these are T-cell independent." (PMID 30569292, 2018).
AIDS (continued). "The progressive loss of CD4 cells eventually results in the loss of the ability to mount a desirable immune response to any pathogen resulting in death of patients in the terminal stage of Acquired Immune Deficiency Syndrome (AIDS)." (PMID 27468351, 2016). "Human Immunodeficiency Virus (HIV) is transmitted by four different routes, including blood transfusion, sexual contact intravenous drug use and mother to child transmission resulting in the destruction of immune cells (CD4+ T cells and development of Acquired Immune Deficiency Syndrome (AIDS)." (PMID 26115456, 2015). "AIDS (the Acquired Immunodeficiency Syndrome), identified in 1981, arose as an epidemic caused by the human immunodeficiency virus, which could result in decreased and dysfunctional CD4 T lymphocytes." (PMID 21739004, 2011). "European and North American cohorts including over 40, 000 patients demonstrated that starting treatment earlier reduced the risk of acquired immune deficiency syndrome (AIDS) or death with those starting before reaching CD4 350 cells/mm3 having the most benefit." (PMID 21999771, 2011). "Likewise, tuberculosis disease synergistically accelerates the progression of HIV-1 infection to Acquired Immune Deficiency Syndrome (AIDS) by inciting viral replication in immunologically activated CD4 cells." (PMID 19229341, 2009). "Low CD4 and high viral load are associated with immunosuppression and AIDS, but viral replication can also accelerate atherosclerosis and non-AIDS mortality." (PMID 41597637, 2026). "The HIV-1 genome is a single-stranded RNA virus belonging to the Retroviridae family that primarily infects CD4+ T cells, leading to progressive immune system deterioration and ultimately causing acquired immunodeficiency syndrome (AIDS)." (PMID 40072080, 2025). "Human immunodeficiency virus (HIV) is a complex retrovirus which replicates in CD4+ T cells and macrophages, destroying the ability of the body to fight other infections and causing acquired immunodeficiency syndrome (AIDS)." (PMID 40143292, 2025). "During the late stages of infection, HIV induces massive depletion of CD4+ T lymphocytes, leading to acquired immune-deficiency syndrome (AIDS)." (PMID 41479924, 2025). "HIV-1 infection progresses more rapidly to AIDS and is associated with higher viral loads and greater CD4 + T cell depletion compared to HIV-2." (PMID 41366989, 2025). "About 80% of patients with acquired immune deficiency syndrome (AIDS) pass away due to illnesses associated with opportunistic infections rather than the virus itself, such as OIPs, mostly when the level of CD4+ T cells drops below 200 cells/μL." (PMID 40557273, 2025). "A CD4/CD8 ratio <0.5 is also an independent predictor of non-AIDS-related and all-cause mortality among PLWH, including those with NHL." (PMID 40723865, 2025). "INRs who remain with low CD4+ counts are at continued risk for AIDS-defining opportunistic infections and other immunodeficiency-related complications, even if HIV viremia is controlled." (PMID 40868140, 2025). "Human immunodeficiency virus (HIV) is responsible for acquired immunodeficiency syndrome (AIDS), a condition characterized by the depletion of CD4+ T lymphocytes, which predisposes individuals to opportunistic infections and, ultimately, death." (PMID 40733502, 2025). "HIV infection begins with acute infection marked by high viraemia and rapid CD4 T‐cell loss, progresses to clinical latency with low‐level viral replication and gradual immune decline, and ultimately leads to AIDS characterized by severe immunodeficiency." (PMID 39865395, 2025). "•Low CD4+ count, the presence of opportunistic infections, and AIDS status are associated with the risk of sarcopenia in PLHIV, regardless of the tool used." (PMID 39752996, 2025). "Higher CD4+ T-cell counts are associated with a lower risk of anti-TB treatment failure in patients with AIDS combined with PTB." (PMID 40510348, 2025).
AIDS (continued). "This increased risk appears mainly due to a high prevalence of previous AIDS and a lower CD4 cell count in 4DR-PWH." (PMID 40749106, 2025). "Nonetheless in our subjects, co-infection with L. infantum and HIV, in both the HIV/Leish and AIDS/VL groups, was associated with higher T cell activation markers in CD4+T and CD8+ T cells." (PMID 40096173, 2025). "Advanced disease was defined as CD4 T count <200 cells/mm3 or the presence of an acquired immune deficiency syndrome (AIDS)-defining illness." (PMID 40559606, 2025). "To date, the only association between CD4 count and the relative risk of developing a malignancy with an established viral pathogenesis is with the known AIDS-defining malignancies." (PMID 41200368, 2025). "Over 30% of PWH who initiate cART with low CD4 counts experience poor CD4 T cell reconstitution, correlated with a higher risk of non-AIDS-related complications." (PMID 40779581, 2025). "HIV-2 infection typically progresses more slowly to AIDS and is associated with lower viral loads and a slower decline in CD4 + T cell counts compared to HIV-1." (PMID 41366989, 2025). "PCP is associated with states of immunodeficiency such as AIDS; the lower the CD4 count, the higher the incidence of the disease." (PMID 40677426, 2025). "Another French cohort found that interruption of medical care led to a significant decrease in CD4 levels and was independently associated with the development of AIDS (odds ratio [OR], 2.54 [95% CI, 2.10–3.09]) and death (OR, 2.65 [95% CI, 1.94–3.61])." (PMID 40176257, 2025). "In our case, the CD4 count at CMV diagnosis was maintained above the AIDS-related risk threshold of 50/mm3." (PMID 40949093, 2025). "Her outpatient labs confirmed a diagnosis of AIDS with a CD4 count of 34, placing her at risk of several opportunistic infections including CMV, and HIV RNA >700,000 two weeks prior." (PMID 39981470, 2025). "In view of this, the findings of the study allow us to infer that patients with a null genotypic profile are less susceptible to AIDS, since allelic deletions increase the chances of CD4+ TL counts being greater than or equal to 350 cells/mm3." (PMID 40867808, 2025). "In this case, uncontrolled viral replication is associated with rapid CD4+ T cell count decline, and progression to AIDS within 1–2 years from infection, much faster than average HIV-1 infection." (PMID 39842407, 2025). "Both viruses predominantly target CD4+ T cells, thereby causing immune dysfunction and eventually progressing to AIDS." (PMID 40725130, 2025). "While cART alone slows the progression to AIDS and, by restoring CD4 counts, can cause KS regression in one-third of cases, other PLWH experience KS despite HIV suppression and near-normal CD4 counts (15, –, 19)." (PMID 40237497, 2025). "For instance, PLHIV with a CD4+ T-cell count below 100 cells/μL (in AIDS stage) are more susceptible to developing esophageal candidiasis, toxoplasmic encephalitis, and primary central nervous system lymphoma (PCNSL)." (PMID 40260259, 2025). "CD4+ αβ T lymphocytes play a crucial role in protective immunity to M.tb, as demonstrated by the substantial vulnerability to TB of patients with AIDS (relative risk = 18.0 [95% CI: 15–21])." (PMID 40446017, 2025). "Human immunodeficiency virus (HIV), a retrovirus of the Lentivirus genus, targets CD4+ T cells, causing immune dysfunction and AIDS." (PMID 39918304, 2025). "A lower CD4 count indicates a greater degree of immune system impairment and an increased risk of opportunistic infections, AIDS-related morbidities, and death." (PMID 40390714, 2025). "Studies on natural HIV-1 control have identified a subgroup of PWH termed HIV controllers who naturally achieve viral control in the absence of ART for 2–10 years, maintain normal peripheral blood CD4+ T cell levels and have a low risk of progression to AIDS." (PMID 40936922, 2025).
AIDS (continued). "Human Immunodeficiency Virus 1 (HIV-1), which causes Acquired Immune Deficiency Syndrome (AIDS), predominantly infects CD4+ T cells, leading to their progressive depletion and immune dysfunction." (PMID 41218081, 2025). "Virus-specific immune dysfunction exacerbates this scenario, as CD8+ and CD4+ T-cell responses against HHV-8 antigens are frequently deficient in both AIDS-associated and classic KS patients, permitting HHV-8 reactivation from latency." (PMID 40723356, 2025). "Nevertheless, the two parameters are closely associated since AIDS appears primarily with low CD4 counts." (PMID 39868926, 2025). "The incidence of HIV-related deaths and the development of AIDS are due to a continuous immunodeficiency associated with the depletion of CD4+ T lymphocytes, compromising the immune system." (PMID 40867808, 2025). "It is important to emphasize that CD4+ count ≤ 200 cells/mm3 is a factor strongly associated with the risk of AIDS mortality." (PMID 39057375, 2024). "Our study showed a correlation between the presence of AIDS and COVID-19 and an increased risk of D-VL, and among high levels of Nadir CD4+ T-cells, longer duration of therapy, higher prescriber’s perception of adherence, and a reduced risk of D-VL." (PMID 38787211, 2024). "The reduced CD4 + helper cell count, and the history of AIDS-defining and HIV-associated diseases imply that the diagnosis of HIV had been delayed for an extended period." (PMID 38581028, 2024). "In the Italian ICONA cohort and a Thai cohort low CD4:CD8 ratio was associated with an increased risk of non-AIDS events, which included a composite endpoint of malignancies, cardiovascular, renal, and hepatic events." (PMID 38092042, 2024). "The ratio of CD4+ T lymphocytes to CD8+ T lymphocytes (CD4+/CD8+ ratio) is an immunologic measure associated with increased risk of non-AIDS comorbidities among PLWH." (PMID 38420256, 2024). "Mortality post transition to adult care for adults LWPaHIV is predictable; the associated lower CD4 count exiting paediatric care and a prior AIDS diagnosis in childhood highlighted the continuing impact of early childhood events much later in adult life." (PMID 38668535, 2024). "Approximately 20% of individuals who initiate cART with low CD4 counts experience poor CD4 T cell reconstitution, which correlates with a higher risk of non-AIDS-related complications." (PMID 39763958, 2024). "Zhang and colleagues identified a baseline CD4+ T cell count of <50 cells/μL as one of the most critical risk factors for HIV/AIDS-related mortality." (PMID 38454987, 2024). "The direction of the predictors was derived from our descriptive analyses, which indicated that the lower the CD4 count at baseline and “yes” in regard to a previous AIDS event, the higher the risk of developing an AIDS-defining condition." (PMID 38381307, 2024). "In the 1980s, early in the acquired immune deficiency syndrome (AIDS) pandemic, the monitoring of CD4 T-cell counts became an essential part of AIDS diagnosis." (PMID 39408593, 2024). "HIV patients with low CD4 counts due to advanced AIDS are at the risk of developing renal syndromes and neurological complications such as hyperreflexia and hyporeflexia, which can lead to urinary stasis and ultimately infection." (PMID 38746741, 2024). "A nadir CD4 cell count ≥50/μL was associated with lower odds of HIV/AIDS-related deaths (aOR for CD4 cell count 200–349/μL, 0.26 [95% CI.12–.51]), as was diabetes (0.26 [.06–.76]) and hypertension (0.45 [.27–.75])." (PMID 38214897, 2024). "Gingival erythema and oral tongue leukoplakia are associated with a significant decrease in the CD4 count and are warning signs of progression to AIDS." (PMID 38360735, 2024). "Results for the AIDS or death cause-specific hazard showed a strong dependence on the observed most recent CD4 counts, which makes the conditional independence assumption unreasonable." (PMID 39449049, 2024).
AIDS (continued). "Patients with high CD4 counts who initiate ART late had a higher risk of AIDS-related death than those with low CD4 counts who start ART early." (PMID 39058196, 2024). "Specifically, deaths related to NADCs were linked to advancing age, CD4 count < 200 cell/μl, and AIDS comorbidity documented by two studies each." (PMID 38549952, 2024). "Low CD4:CD8 ratios are independently of CD4 cell counts associated with increased risk of AIDS-defining and infection-related malignancies in antiretroviral-treated people with human immunodeficiency virus (HIV)." (PMID 38092042, 2024). "HIV-1 infection leads to the development of acquired immunodeficiency syndrome (AIDS) associated with the depletion of CD4+ T cells, mainly by apoptosis which predicts further pathogenicity." (PMID 38534416, 2024). "HIV/AIDS increases the risk of developing active TB mainly by killing CD4+ T cells in the blood, lymphoid tissues, and mucosa." (PMID 38919722, 2024). "Apoptosis is one of the presumptive causes of CD4+T cell depletion and progression to acquired immunodeficiency syndrome (AIDS)." (PMID 39329696, 2024). "Survivors of AIDS-associated PML had higher CD4 cell counts than patients with active PML, indicating some degree of immune recovery on antiretroviral treatment." (PMID 39086476, 2024). "The immune suppression in AIDS is the loss of CD4 cells in blood and other areas making them prone to active TB infection as CD4 cells are known to stimulate alveolar macrophages, which engulf the TB bacilli." (PMID 39050280, 2024). "HAART use is associated with improved immunity(CD4 count) and better virologiccontrol, reducing AIDS-associated morbidity and mortality in patients with HL." (PMID 38961368, 2024). "The analysis of the Korea HIV/AIDS cohort study data shows that CD4 cell count is positively associated with residual life to the onset of dyslipidemia but the effect is not statistically significant." (PMID 38368350, 2024). "Declining CD4 + T-cell count is a key factor for AIDS diagnosis and helps to determine the need for associated prophylaxis measures." (PMID 39822268, 2024). "HIV Nef secreted in exomes are also thought to trigger CD4+ T cell apoptosis, thereby contributing to the hallmark CD4 lymphopenia seen in AIDS." (PMID 39086659, 2024). "The progressive loss of CD4 + T cells and consequent immunodeficiency eventually result in acquired immunodeficiency syndrome (AIDS)." (PMID 38743119, 2024). "Selenium supplementation in PLWHIV has been associated with decrease in CD4+ T cell decline, delay progression to AIDS and lower diarrheal morbidity." (PMID 39351495, 2024). "In HIV-infected individuals, progressive loss of CD4+T cells causes AIDS (Acquired Immunodeficiency Syndrome)." (PMID 38267841, 2024). "Human immunodeficiency virus (HIV) mainly invades CD4+T lymphocytes and destroys the host immune system, causing acquired immune deficiency syndrome (AIDS)." (PMID 39902182, 2024). "Age (aHR, 1.2; 95% CI, 1.03–1.39; P = .01) and AIDS diagnosis (aHR, 3.2; 95% CI, 3.06–27.9; P = .001) were associated with TB development, whereas high CD4 count was protective against TB (aHR, 0.18; 95% CI.06–.61; P = .005)." (PMID 39257676, 2024). "It is well known that HIV-1 pathogenicity is associated with the depletion of CD4+ T cells leading to the development of AIDS." (PMID 38534416, 2024). "This is further supported by two different studies included in this review, which observed a positive association of Ruminococcaceae with a higher CD4 count (>200 cells/μL) among INRs and in naïve pre-AIDS PLHIV." (PMID 38804398, 2024). "It is essential to track immune perturbations related to insufficient CD4 T-cell recovery in PWH on suppressive ART as those with incomplete reconstitution are at a greater risk of non-AIDS-related morbidity and mortality." (PMID 39287441, 2024).